SDHA (succinate dehydrogenase complex flavoprotein subunit A)
Diseases named in the same sentence as SDHA in open-access papers (continued):
Sharing a sentence is not in itself a finding about the gene and the disease.
renal carcinoma (14 papers, 2017 to 2025). A carcinoma arising from the epithelium of the renal parenchyma or the renal pelvis. "Among the variants, the greatest interest was placed in SDHA, given studies implicating this gene in renal cancer pathogenesis." (PMID 30680959, 2019). "Other studies reported that the upregulation of SDHA inhibited migration and invasion of renal carcinoma cells." (PMID 36291881, 2022). "This work generally supports the idea that an Ala45Thr substitution in the SDHA (OMIM: 600857) gene is a risk factor, and implicates other potential predisposing factors for a family with a high incidence of renal cancers." (PMID 30680959, 2019). "We extended these findings to 786-O renal carcinoma cells, another model with high mitochondrial activity, and observed a significant reduction in cell proliferation upon SDHA knockout, indicating that SDHA’s role in supporting proliferation is not cell-line-specific." (PMID 40060604, 2025). "Highlighting here a patient case with neuroblastoma, renal cancer & GIST from germline SDHA." (PMID 38885448, 2024).
neuroblastoma (13 papers, 2009 to 2024). Neuroblastoma (NB) is the most common solid, extracranial childhood tumor. "Outstandingly, we identified the same second SDHA pathogenic variant c.1840C>T (p.Q614*) in more than one neoplasm, the neuroblastoma, and the GIST diagnosed 34 years apart." (PMID 38885448, 2024). "The only study that up to now suggesting the possible role of SDHA as a predisposing factor for other tumor types reported the development of neuroblastoma in one SDHA-mutation carrier showing the inactivation of the second allele." (PMID 35059314, 2021). "It was observed that a 3-year-old patient diagnosed with primary neuroblastoma carried the germline non-sense mutation in the SDHA gene, while a 5-year-old patient from a Spanish family was diagnosed with carrying a germline deletion in SDHB." (PMID 34768850, 2021). "Previous studies with qPCR have found HPRT1 and SDHA to show low expression variability in primary neuroblastoma and also, specifically for the SY5Y line, GAPDH, M-RIP, and POLR2F were found to be reliable genes to be used as normalization factors." (PMID 34066513, 2021). "By contrast, in one study, 1 patient with germline SDHA mutation was found to be associated with GIST complicated by RCC, whereas in another study, germline SDHA mutation was found to be associated with GIST in 2 patients and neuroblastoma in 1 patient." (PMID 30854332, 2019). "In neuroblastoma pediatric patients, alterations in the SDHA and SDHB genes have been found." (PMID 34768850, 2021). "Commercially available pharmacological inhibitors of SDHA (malonate), HSP90AB1 (geldanamycin), and VDAC3 (TRO19622) were used for functional evaluation of the TDP-43 genetic-interacting loci in N2a neuroblastoma cells." (PMID 33803845, 2021). "In this study, SDHA, UBC and GAPDH housekeeping genes were used as endogenous controls based on previous data which showed these genes to be most stably expressed in human neuroblastoma cells." (PMID 19445671, 2009).
cardiomyopathy (10 papers, 2020 to 2025). A disease of the heart muscle or myocardium proper. "A study has found that patients with a homozygous missense mutation in the SDHA gene have reduced Complex II activity by up to 60% and 85% in skeletal and heart muscles, respectively, and they develop cardiomyopathy." (PMID 34827632, 2021). "One of the rare cases of documented autosomal inheritance of SDHA subunit defect was linked to bilateral optic atrophy, ocular movement disorder, progressive polyneuropathy, psychiatric involvement, and cardiomyopathy." (PMID 32290794, 2020). "Mutations in SDHA, SDHB and SDHAF1 were reported in leukodystrophy, Leigh syndrome and cardiomyopathy, and infantile leukoencephalopathy." (PMID 32290794, 2020). "Finally, we also identified four variants of uncertain significance in cardiomyopathy-associated genes (TNNT2, PRDM16, LDB3, and SDHA) in three fetuses." (PMID 33553264, 2020). "Alterations of Complex II due to inherited homozygous mutations of its catalytic components (SDHA, SDHB, and SDHC) and of the SDHAF1 assembly factor are associated with a reduced number of neuromuscular pathologies, including Leigh syndrome, cardiomyopathy, and infantile leukodystrophies." (PMID 34827632, 2021). "A number of previous studies have demonstrated a decrease in respiratory chain complex I activity as well as ATP synthase activity, but SDHA activity did not change in mouse models of human DCM and other cardiomyopathies." (PMID 37740197, 2023).
ovarian carcinoma (10 papers, 2013 to 2025). A malignant neoplasm originating from the surface ovarian epithelium. "In our previous work, mechanistic studies revealed that SDHA upregulation in ovarian cancer is associated with robust mitochondrial OXPHOS and ATP production, which are essential for the viability of tumor cells." (PMID 40563592, 2025). "In ovarian cancer, overexpression of SdhA is common in ovarian carcinoma patients and was associated with high mitochondrial metabolism in cancer models." (PMID 38893151, 2024). "Increased SDHA expression has been associated with reduced cell proliferation in ovarian cancer cells." (PMID 39765841, 2024). "As predicted, the overexpression of SDHA in ovarian cancer cell lines was associated with increased fumarate levels (as assessed by Fumarate Assay)." (PMID 36291881, 2022). "We observed that SDHA overexpression was associated with both higher number and size of ovarian cancer cell colonies, while the SDHA KD reduced formation of cell colonies." (PMID 36291881, 2022). "While mutations of SDH subunits are very rare in ovarian cancer, the amplification or overexpression of a SDHA subunit is highly prevalent in this tumor type (~20% tumors)." (PMID 36291881, 2022). "Our data underline the unappreciated role of SDHA in reprogramming of ovarian cancer metabolism, which represents a new opportunity for therapeutic intervention." (PMID 36291881, 2022). "A study has uncovered that elevated SDHA causes metabolic enhancement, marked by an increase in mitochondrial respiration and glycolysis, resulting in a higher ATP production rate, as seen in ovarian cancer." (PMID 40119440, 2025). "We evaluated the effect of SDHA overexpression on tumor growth, metastasis, and mouse survival in vivo using immunocompetent mouse models of ovarian cancer." (PMID 40563592, 2025). "In our earlier research, to identify compounds that selectively target ovarian cancer cells overexpressing SDHA, we screened a library of 64 anti-metabolic agents." (PMID 40563592, 2025). "In this study, we studied the unique metabolism of ovarian cancer overexpressing SDHA and identified key vulnerabilities of tumors with the SDHA-gain-of-function phenotype that can be exploited for therapeutic benefit." (PMID 40563592, 2025). "Methods and Results: Our work shows that the upregulation of mitochondrial enzyme SDHA is particularly prevalent in ovarian carcinoma." (PMID 40563592, 2025). "Here, to expand our studies exploring the impact of SDHA overexpression on tumor biology, we obtained innovative ovarian cancer cell lines derived from murine fallopian tube epithelium (mFTE) from Dr. Weinberg." (PMID 40563592, 2025). "We examined the unique metabolism of ovarian cancer overexpressing succinate dehydrogenase subunit A (SDHA) and identified a distinctive vulnerability of these tumors to agents targeting key regulators of the OXPHOS pathway, particularly the LRPPRC protein." (PMID 40563592, 2025). "We discovered that a common feature of high-OXPHOS tumors is significantly overexpressed mitochondrial enzyme succinate dehydrogenase subunit A (SDHA), which is particularly prevalent in ovarian carcinoma (~20% of cases)." (PMID 40563592, 2025). "In this work, we showed that the aberrantly upregulated SDHA is a therapeutically relevant target in ovarian cancer." (PMID 40563592, 2025). "To gain insight into the metabolic flux of glucose (Glu) and glutamine (Gln) in SDHA-overexpressing ovarian cancer cells and to specifically determine if glutamine replenishes TCA cycle intermediates, we performed stable-isotope tracing." (PMID 40563592, 2025). "Our in vivo studies using mouse models of ovarian cancer showed that SDHA overexpression contributed to robust orthotopic tumor growth and metastasis, substantially reducing mouse survival." (PMID 40563592, 2025). "Our Seahorse-based assays showed that LRPPRC plays an essential role in promoting OXPHOS in SDHA-overexpressing ovarian cancer cell lines." (PMID 40563592, 2025).
ovarian carcinoma (continued). "The top 10 genes with most deleterious mutations in the Chinese ovarian cancer population were MC1R (12%), MLH1 (9%), PRKDC (8%), KIF1B (8%), FANCM (7%), FANCI (6%), PRSS1 (6%), SDHA (6%), BRCA2 (6%), and CFTR (5%)." (PMID 38817903, 2024). "Lastly, we implemented a drug screening strategy and identified anti-metabolic compound shikonin, which demonstrated a specific and potent efficacy against SDHA overexpressing ovarian cancer cells." (PMID 36291881, 2022). "To evaluate the SDHA biological functions in ovarian cancer, we assessed the effect of SDHA overexpression on cell proliferation and in vivo tumor growth." (PMID 36291881, 2022). "Here, we evaluated the effect of a conditional overexpression of SDHA or stable SDHA KD in ovarian cancer cell lines on mitochondrial respiration and glycolysis." (PMID 36291881, 2022). "Further, to determine the effect of SDHA overexpression on tumor growth in vivo, we subcutaneously implanted 5 × 106 of SDHA dox-inducible ovarian cancer cells into the flank of NOD/scid mice." (PMID 36291881, 2022). "In this work, using various in vitro and in vivo ovarian cancer models, we investigated the biological consequences of SDHA overexpression and its impact on tumor phenotype." (PMID 36291881, 2022). "We also identified an anti-metabolic compound shikonin with a potent efficacy against SDHA overexpressing ovarian cancer cells." (PMID 36291881, 2022). "Collectively, our findings demonstrated a tendency to reduced ovarian cancer cell proliferation following SDHA overexpression in vitro." (PMID 36291881, 2022). "We assessed an enzymatic activity of succinate dehydrogenase in our ovarian cancer cell lines conditionally overexpressing SDHA or SDHA KD cells using Succinate Dehydrogenase Activity Assay." (PMID 36291881, 2022). "Collectively, we identified a highly potent compound shikonin that effectively kills SDHA overexpressing ovarian cancer cells." (PMID 36291881, 2022). "First, we screened the anti-metabolic agents across 4 ovarian cancer cell lines, including those endogenously overexpressing SDHA, and those characterized by naturally low SDHA expression levels." (PMID 36291881, 2022). "Together, these data validated a proper enzymatic function of exogenously overexpressed SDHA in ovarian cancer cell lines." (PMID 36291881, 2022). "In the present study, we set out to investigate the differences in bioenergetic profiles of ovarian cancer cell lines overexpressing SDHA vs. their respective SDHA-low counterparts." (PMID 36291881, 2022). "The ovarian cancer cell lines conditionally overexpressing SDHA (Caov3-SDHA and OVCAR3-SDHA) were also significantly more sensitive to shikonin than respective controls." (PMID 36291881, 2022). "Further, we showed that the overexpression of SDHA enhanced ovarian cancer metabolism reflected as increased mitochondrial respiration and ATP production rate." (PMID 36291881, 2022). "Next, we analyzed the frequency of SDHA amplification across different tumor types, and found that ovarian cancer shows the highest SDHA amplification rates out of the 25 diverse malignancies." (PMID 36291881, 2022). "In the present study, our initial findings highlighted a potential importance of SDHA upregulation in ovarian cancer and set the stage for further more rigorous research." (PMID 36291881, 2022). "We discovered that the overexpression of mitochondrial enzyme succinate dehydrogenase (SDHA) is particularly prevalent in ovarian carcinoma and promotes highly metabolically active phenotype." (PMID 36291881, 2022). "We discovered that the overexpression of mitochondrial enzyme succinate dehydrogenase (SDHA) is highly prevalent in ovarian carcinoma patients and contributes to elevated mitochondrial metabolism in ovarian tumor models." (PMID 36291881, 2022). "In summary, our work provided novel insights into the role of SDHA upregulation in reprogramming of energy metabolism in ovarian cancer." (PMID 36291881, 2022).
ovarian carcinoma (continued). "Altogether, our study demonstrated that SDHA upregulation frequently occurs in ovarian cancer and contributes to reprogramming of energy metabolism towards highly metabolically active phenotype." (PMID 36291881, 2022). "Further, we observed that ovarian PDXs and established ovarian cancer cell lines exhibit a range of SDHA expressions." (PMID 36291881, 2022). "We carried out a screen of anti-metabolic agents, and identified a potent drug shikonin that more effectively kills SDHA overexpressing ovarian cancer cells than SDHA-low counterparts." (PMID 36291881, 2022). "To better understand cellular energetics in SDHA overexpressing ovarian cancer cells deprived of nutrients, we quantified ATP production rate." (PMID 36291881, 2022). "Next, to assess the glycolytic function of SDHA-high vs. SDHA-low ovarian cancer cell lines, we performed the Seahorse XF Glycolysis Stress Test, which directly measures the extracellular acidification rate (ECAR) in live cells." (PMID 36291881, 2022). "In different sets of experiments, we deprived ovarian cancer cells of glucose or glutamine to determine if SDHA overexpression redirects cellular metabolism in response to nutrient deficiency." (PMID 36291881, 2022). "As another approach to assess the impact of SDHA upregulation on cellular metabolism, we tested ovarian cancer dependence on nutrients essential for tumor growth." (PMID 36291881, 2022). "Lastly, we identified an anti-metabolic compound shikonin, which demonstrated a potent anti-tumor efficacy against SDHA overexpressing ovarian cancer cells." (PMID 36291881, 2022). "To identify agents specifically targeting the SDHA overexpressing ovarian cancer cells, we utilized a custom compound library (from Seleckchem) composed of 64 anti-metabolic compounds." (PMID 36291881, 2022). "Overall, we strive to advance scientific knowledge by uncovering the previously unappreciated role of SDHA in reprogramming of ovarian cancer metabolism, which holds untapped opportunities for therapeutic intervention." (PMID 36291881, 2022). "We also expanded our panel of genetically engineered human ovarian cancer cell lines with conditional (dox inducible) SDHA overexpression (SDHA-OE) or stable SDHA knockdown (KD), as well as established human fallopian tube cell lines (FT190 and FT194) as controls." (PMID 40563592, 2025). "Thus far, we have studied the effects of SDHA overexpression solely with the use of human ovarian cancer models." (PMID 40563592, 2025). "The SDHA gene amplification is highly prevalent in ovarian cancer, and has been reported in a considerably higher frequency in ovarian tumors than in many other malignancies (TCGA data) indicating its potential role in reprogramming of ovarian cancer metabolism." (PMID 36291881, 2022). "Importantly, we found that ovarian cancer cells with elevated SDHA are more vulnerable to deprivation of both glucose and glutamine, which is associated with a substantial reduction of ATP yield in those cells." (PMID 36291881, 2022). "Further, we evaluated endogenous levels of SDHA in ovarian cancer cell lines by WES." (PMID 36291881, 2022). "We investigated the functional consequences of SDHA overexpression in ovarian cancer." (PMID 36291881, 2022). "The genomic data demonstrated that the SDHA gene amplification or overexpression is highly prevalent in ovarian carcinoma patients (19% of all cases) compared to other tumor types, which indicates its potential importance in reprogramming of ovarian cancer metabolism." (PMID 36291881, 2022). "However, there was a tendency towards improved overall survival of ovarian cancer patients with SDHA amplification/overexpression." (PMID 36291881, 2022). "As a next step, we functionally validated our ovarian cancer models and showed that the conditional overexpression of SDHA in ovarian cancer cell lines significantly increased succinate dehydrogenase enzyme activity, while SDHA knockdown suppressed its activity." (PMID 36291881, 2022).